KRAS (KRas proto-oncogene, GTPase)
Diseases named in the same sentence as KRAS in open-access papers (continued):
Sharing a sentence is not in itself a finding about the gene and the disease.
tumor (continued). "For instance, Erastin and RSL3 caused ferroptosis in human tumor cells engineered to express HRASG12V at lower concentrations than wild-type isogenic cells, and inhibiting GPX4 re-sensitized KRAS-expressing NSCLC cell lines (A549 and H460) made radioresistant." (PMID 34485382, 2021). "Recently, rare KRAS mutations detected in cfDNA were demonstrated derived from clonal hematopoiesis, not from tumor." (PMID 34680277, 2021). "Oncogenic KRAS plays a crucial role in tumor development and progression, promoting cell proliferation, cell death resistance, evasion from immune system, and metastasis; moreover, it contributes to the tumor microenvironment modifications and the typical cancer cell metabolic reprogramming." (PMID 33670598, 2021). "The results showed that IL-20RA was correlated with several classic tumor-related signaling pathways, such as KRAS, hypoxia, and EMT pathway, which might lead to promotion of tumor proliferation, migration and invasion." (PMID 34336707, 2021). "Intriguingly, conditioned media from these tumour cell-educated PSCs could further alter the tumour cell phosphoproteome, beyond the cell-autonomous changes driven by oncogenic KRAS." (PMID 34638468, 2021). "At the time of diagnosis, the proportion of patients with pleural metastases, as either the only metastatic site or concurrent with other metastatic sites, was higher for patients with KRAS wt tumours (13.1%) than patients with KRAS mut tumours (6.5%, p < 0.001)." (PMID 34503114, 2021). "This compound suppresses the growth of KRAS(G13D) tumours in vivo." (PMID 35582302, 2021). "In addition, NKX2‐1/TTF‐1‐regulated microRNA‐532‐5p has a tumour suppressive role by targeting KRAS in LADs." (PMID 34014042, 2021). "Plasma detected and tumor sample absent variants were also observed in two other patients, harboring one KRAS and one BRAF mutation, respectively." (PMID 34217228, 2021). "Synergistic effects of RTK inhibitors combined with KRAS blockade may vary across different tumor cell types." (PMID 33777798, 2021). "If inhibition of oncogenic KRAS can reduce these tumour evasion mechanisms, combination KRAS-G12C inhibition with checkpoint blockade could circumvent some limitations of either strategy alone." (PMID 34200676, 2021). "In addition, statin administration in combination with oxaliplatin, an immunogenic cell death inducer, was found to elicit an effective antitumor immune response in genetically engineered KRAS tumor models." (PMID 34947990, 2021). "However, even with the low frequency of tumor formation, about 50% of KRAS KO tumors still developed peritoneal, liver, or splenic metastases." (PMID 33674596, 2021). "Tumor-associated epithelial ATII-like clusters and the epithelial cluster specific to mutant-KRAS ADCs, are positive for the oncogene BMI-1, and, according to our hypothesis, responsive to PTC596 in vivo treatment." (PMID 33854168, 2021). "This molecule is able to reduce RAS-GTP and pERK levels and decrease the growth of the majority of tumor cells harboring a KRAS mutation, including G12D and G12V variants, unlike KRAS (G12C) selective inhibitors." (PMID 34063682, 2021). "Of interest, reducing zDHHC20 levels impairs tumor formation in a KRAS-mutant mouse model." (PMID 33219126, 2021). "As it regards LC, sulfasalazine has been recently reported to selectively kill KRAS-mutant LC, indicating that it might be a good drug candidate in this tumor type." (PMID 34485382, 2021). "Treatment effect may be affected by primary tumor location and KRAS subtype, with greater benefit seen in left-sided cancers and those with KRAS codon 12/13 mutations." (PMID 34538072, 2021).
tumor (continued). "In the context of tumor biology, GPR31 was identified to mediate KRAS membrane association and is crucial for proliferation and survival of KRAS-dependent tumors suggesting that GPR31 may represent a target for anti-RAS therapy." (PMID 34440817, 2021). "Finally, a number of previous studies have shown that KRAS mutant cancer cells have immunoregulatory effects that extend beyond the ECM changes reported in our study to affect other elements of the tumor microenvironment." (PMID 33817986, 2021). "Furthermore, targeting the α4–α5 dimerization interface with an inducible NS1 monobody results in the inhibition of KRAS-driven tumor formation in vivo." (PMID 34680951, 2021). "The expression of SAA transcript was evaluated according to KRAS status, where levels were significantly increased in KRAS mutated but not wild-type tumour biopsies." (PMID 34203378, 2021). "The bispecific VHH triggered CD16- and EGFR-dependent activation of NK cells and subsequent lysis of tumor cells, regardless of the KRAS mutational status of the tumor." (PMID 34771609, 2021). "In fact, the founding members of the RAS gene family in humans (KRAS, NRAS and HRAS) are the most common oncogenes in human cancer, whereas mutations that permanently activate RAS are found in almost 25% of all human tumours and up to 90% in specific types of malignancies." (PMID 34948093, 2021). "Collectively, these results indicate that KRAS-Mφ are able to elicit a significant increase of the aerobic glycolysis of tumor cells, which subsequently may result in enhanced proliferative and invasive capacities." (PMID 33833221, 2021). "In the present study, of 60 PTCs, 41 were BRAF-mutated (68.3%) and TERT promoter-mutated (3.5%), in contrast to no NRAS or KRAS mutation in the tumor tissues." (PMID 33915745, 2021). "WT copy of the KRAS gene was frequently retained in lines harboring G12D mutations, regardless of the tumor type." (PMID 34573384, 2021). "The tumor tissue was positive for KRAS, STK11, and PDL1 < 24%." (PMID 34298855, 2021). "Neither tumor nor stromal expression of CD200 or CD200R demonstrated significant associations with epidermal growth factor receptor (EGFR) or KRAS mutation status in NSCLC patients." (PMID 33804482, 2021). "Furthermore, heterozygous mutations in NR5A2 rendered the mouse pancreas more susceptible to tissue damage, inhibited tissue regeneration, and cooperated with the mutant KRAS to promote tumor progression." (PMID 34277436, 2021). "Then, we sought to determine whether the MEKi treatment can enhance the oHSV replication in the tumor cells with BRAF wt and the upstream KRAS mutations." (PMID 34578339, 2021). "Specific conclusions based on tumor stage, ctDNA concentration and mutations other than KRAS were not possible to derive." (PMID 34298594, 2021). "KRAS G12V mutation was detected in four (25%) tumor DNA samples and not detected in circulating DNA samples collected before treatment or during follow-up." (PMID 34203201, 2021). "More recently, other studies have also reported emergence of KRAS mutations in liver metastases after anti-EGFR treatment, highlighting the role of intra-tumour heterogeneity as a major contributing factor for intrinsic and/or acquired resistance to anti-EGFR mAbs." (PMID 33562755, 2021). "While the median PFS of responders was six months with single-agent sotorasib, future evaluation of KRAS inhibitors with tumor-informed precision combinations may lead to more effective targeting." (PMID 34198738, 2021). "This might explain why supplementing the diet with the antioxidants vitamin E markedly increases tumor progression and reduces survival in mouse models of KRAS–induced LC." (PMID 34485382, 2021). "In addition, KRAS mutations can co-exist with other mutations in significant genes in cancer (e.g., STK11 and KEAP1) which induces tumor heterogeneity and promotes different responses to therapies." (PMID 35096591, 2021).
tumor (continued). "The sequencing of protein-coding exons, e.g., KRAS, BRAF and PIK3CA, in circulating tumor DNA (ctDNA) samples from MM patients revealed that it predicted 96% of mutations detected in matched BM-derived tumor DNA samples with >98% specificity." (PMID 34299097, 2021). "This cell-extrinsic mechanism awards KRAS a critical role in engineering a permissive microenvironment to promote tumor malignancy, and may present new insights on potential therapeutic defense strategies against mutant KRAS tumors." (PMID 33833221, 2021). "Newly identified tumor-enriched subpopulations were discovered, of which one represents a novel specific epithelial tumor cluster, matching a signature of markers that we also selectively identified in the human mutant-KRAS-specific subpopulation." (PMID 33854168, 2021). "Moreover, KRAS activation reduces tumor immunogenicity, downregulating MHC-I molecules and leading to inability of CD8+ T cells to recognize tumor cells [27•]." (PMID 34110510, 2021). "Based on these results, KRAS-mutant tumor cells might have more aggressive behavior on tumor progression and then affect the stroma genomic features via EMT; thus, we conducted some experiments to validate this condition in vitro." (PMID 34733795, 2021). "The two tumor tissues that was positive for KRAS G12C mutation by CRISPR–Cas12a was negative by PCR and direct sequencing analysis." (PMID 33467412, 2021). "Once KRAS mutations occur, the hydrolysis of GTP is disrupted and/or nucleotide exchange is enhanced, and then KRAS accumulates in an active state, contributing to continuous activation of downstream signaling pathways, thereby promoting tumor cell proliferation." (PMID 34742312, 2021). "Within each cancer type, the relative abundance of the mutational signatures was generally consistent across tumor samples, regardless of the KRAS allele." (PMID 33753749, 2021). "SAAHIGHALOX5LOW tumours harbouring a wild-type KRAS genotype were also observed, albeit at a lower frequency, to suggest that this endotype is not restricted to KRAS mutated patients." (PMID 34203378, 2021). "VISTA antagonism by CA170 revealed strong efficacy against lung tumorigenesis with broad immunoregulatory functions that influence effector, memory and regulatory T cells, and drives an adaptive T cell tumor-specific immune response that enhances the efficacy of the KRAS vaccine." (PMID 34302042, 2021). "Taken together, these findings suggest that the crosstalk between KRAS and TAMs may function as a previously unappreciated tumor-supportive mechanism in the tumor microenvironment." (PMID 33833221, 2021). "Therefore, we defined “genetic regression” as the loss of the genetic alterations in a specific key-driver gene from the primary tumor to the metastatic one (i.e., mutant KRAS (mutKRAS) in primary tumor→wild-type KRAS (wtKRAS) in metastases)." (PMID 34439390, 2021). "The reason may be that MEK inhibitors can induce signal feedback of the MAPK pathway in KRAS-mutant tumours, resulting in drug resistance to MEK inhibitors." (PMID 34012925, 2021). "Significant efficacy has been demonstrated in the treatment of tumors with various polyphenols, in particular the majority of polyphenols that entertain specificity toward tumor cells that express mutated KRAS and not so in normal cells." (PMID 34744708, 2021).
tumor (continued). "Interestingly, the expression of oncogenic HRAS or KRAS has been shown to induce tumor formation in vivo in a doxycycline-dependent manner, and withdrawal of the drug resulted in tumor shrinkage." (PMID 33793658, 2021). "Primary tumor tissue genotyping resulted KRAS G12S and BRAF V600E mutated, respectively, whereas no RAS neither BRAF mutations were detected by cfDNA analysis." (PMID 34680277, 2021). "The baseline model without inclusion of 3D-QAM (model A) yielded tumor diameter [OR 1.11 (CI 1.05, 1.18)] and KRAS mutation [OR 0.29 (CI 0.09, 0.97)] as statistically significant factors affecting ASR." (PMID 34868968, 2021). "To test whether USP12 downregulation is strictly associated with KRAS mutation in NSCLC, we analysed USP12 transcript levels in human LUAD tumours carrying different types of oncogenic mutations (TCGA-LUAD database)." (PMID 34381028, 2021). "The dependency on KRAS signaling varies across different KRAS mutant cancer types and could reflect the variability in the tumor response, representing a possible mechanism of intrinsic resistance." (PMID 33777798, 2021). "We did not analyze the mechanisms underlying EZH2 overexpression in our tumor cohort, but there is evidence from the literature that NF-kB, MUC1-C, KRAS, MEK-ERK and PI3K-AKT signaling might cause significant EZH2 up regulation in human cancers." (PMID 32303902, 2021). "In multivariable analysis, patients with a tumor diameter with a < 20% increase had notably reduced hazards of death (HR = 0.15, P = 0.01) after adjusting for age, combined surgery, KRAS status, cancer type, mismatch repair (MMR) status, treatment course and cancer differentiation." (PMID 34798858, 2021). "Additionally, EVs delivering siRNA-KRAS were able to successfully silence KRAS in murine tumor tissues, reducing tumor size; the same technology also enabled the delivery of plasmids to successfully replace/restore genes." (PMID 34616741, 2021). "Since the MOA agents listed for SOM meta-clades 21 through 24 have roles in DNA damage, defective CDKN2A, RPTOR and KRAS may contribute to chemosensitivity of tumor cell lines to these agents." (PMID 33909629, 2021). "FTIs were found to lack anti-tumor effect in KRAS (and NRAS) mutant cancers." (PMID 34947990, 2021). "For LUAD tumor cells with the ability to metastasize to the pleura and foster a malignant pleural effusion (MPE), it has been shown that the determining factor is the presence of KRAS activating mutations, which favor the production of CCL2 by the tumor cells." (PMID 33494181, 2021). "We cultured two APC deleted tumor-derived organoid lines, with and without a spontaneous mutation in the KRAS oncogene (abbreviated organoids line A and AK)." (PMID 33972635, 2021). "Most clinical features, including age, sex, tumor stage, microsatellite instability, adjuvant chemotherapy, and KRAS mutation, were not significantly different between the high and low-risk groups in all four cohorts." (PMID 34394098, 2021). "In 13 stage II-III PDAC patients, they identified ~30% of somatic tumor mutations (VAF >1%) in ccfDNA and found evidence of corresponding ctDNA in ~69% of patients that were either the KRAS p.G12D or p.G12C variants (median allele frequency of 0.12%; range: 0.05 to 0.56%)." (PMID 34298235, 2021). "Commonly mutated genes that characterize PDAC (KRAS and CDKN2A) could be found in both tumor samples." (PMID 33764904, 2021).
tumor (continued). "Notably, glutamine is an essential component of redox homeostasis and supports tumor growth of PDAC cells in an oncogenic KRAS-driven manner." (PMID 34944824, 2021). "Further, we did not collect data on molecular abnormalities in primary tumour, e.g. the presence of activating mutations in the KRAS, NRAS and BRAF, or microsatellite instability and defective DNA mismatch repair (dMMR)." (PMID 33971834, 2021). "In mutant-KRAS tumor cells, inhibition of SOS1 led to a 50% reduction in phospho-ERK." (PMID 34845311, 2021). "To study the tumor cell-intrinsic differences in response to commonly used therapies between dMMR and pMMR CRC, we generated a PDO cohort of six dMMR and six pMMR CRC-derived PDOs with annotated primary tumor location (sidedness) and BRAF- and KRAS-mutational status." (PMID 34771595, 2021). "However, a novel RAF/MEK potent inhibitor showed a 60% tumor reduction in RAS-RAF mutated tumors and is being tested in combination with a FAK inhibitor in KRAS mutant LuAD." (PMID 35096591, 2021). "KRAS, BRAF, and PIK3CA mutations are highly concordant between primary tumors and distant metastatic CRC tumors, indicating that either type of tumor tissue could be useful as a source to detect KRAS mutations for the selection of anti-EGFR therapy." (PMID 33652647, 2021). "One study assembled a panel of patient-derived colorectal organoids including tumour organoids harbouring RAS mutations, tumour organoids and colon organoids with wild-type RAS as well as tumour organoids and colon organoids with CRISPR-introduced oncogenic KRAS mutations." (PMID 34321074, 2021). "In CRC, it was notably demonstrated that exosomes were implicated in the transfer of mutant KRAS from mutant cells towards non-mutant KRAS cells, thus providing an increase in tumour growth in vitro." (PMID 33801266, 2021). "We found that protein-degradation of the KRAS isoform in KRAS-mutant tumours, comparing intracellular antibodies and DARPins, could specifically ablate these cells." (PMID 33462327, 2021). "In a case report, objective regression of all seven lung metastases was observed after the transfusion of tumor-infiltrating lymphocytes specifically targeted KRAS G12D, which was identified in tumor-infiltrating lymphocytes obtained from a patient with metastatic colorectal cancer." (PMID 34178645, 2021). "Increased SAA expression and decreased ALOX5 expression resulted in a significant increase in the SAA/ALOX5 ratio in KRAS mutated tumours but not in KRAS wild-type tumours." (PMID 34203378, 2021). "Furthermore, multiple studies have demonstrated that the extracellular regulated kinase (ERK) mitogen-activated protein kinase (MAPK) pathway plays a key role in KRAS-dependent tumor initiation, progression, and maintenance." (PMID 34771675, 2021). "Therefore to achieve the goal we recruited 80 CRC patients and performed KRAS gene sequencing from tumor samples." (PMID 34369256, 2021). "Furthermore, SHP2 plays a central and indispensable role in oncogenic KRAS-driven tumours and promotes tumour development." (PMID 34753486, 2021). "Donor of BKZ-8 did not reveal any therapeutic relevant mutation, while the tumor material of BKZ-9 donor showed mutations in the KRAS gene and in STK11." (PMID 33925297, 2021). "KRAS is a member of the RAS family of proteins which are a part of at least six signalling pathways in a healthy human cell and is the most commonly mutated protein across many human tumour types." (PMID 33562505, 2021). "GSEA revealed that several tumor hallmarks were enriched in the samples with high risk, such as epithelial-mesenchymal transition, inflammatory response, hypoxia, complement, IL2-STAT5 signaling, KRAS signaling (FDR < 0.05) and so on." (PMID 34150627, 2021).